RNU4-50P (RNA, U4 small nuclear 50, pseudogene)
Gene: Small nuclear RNA gene on chromosome 8 (58,814,412 to 58,814,552, reverse strand). Ensembl gene ENSG00000201231.
Homologues: Orthologues: chimpanzee U4 (100% identical). Paralogues in human: RNU4-10P (78% identical), RNU4-49P (77% identical), RNU4-36P (77% identical), RNU4-81P (74% identical), RNU4-32P (73% identical), RNU4-17P (72% identical), RNU4-46P (68% identical), RNU4-15P (67% identical), RNU4-28P (67% identical), RNU4-83P (67% identical), RNU4-51P (67% identical), RNU4-90P (67% identical), and 82 more.